TAAR3P (trace amine associated receptor 3, pseudogene)
Description:
Putative olfactory receptor activated by several primary trace amines.
Synonyms: GPR57; TAAR3; GPR58
Gene: Transcribed unprocessed pseudogene on chromosome 6 (132,608,252 to 132,609,276, reverse strand). Ensembl gene ENSG00000179073.
Subcellular location: Cell membrane
Diseases named in the same sentence as TAAR3P in open-access papers:
TAAR3P is named in the same sentence as 5 diseases in open-access papers, as found by Europe PMC text mining. Sharing a sentence is not in itself a finding about the gene and the disease.
TAAR3P shares sentences with these, for which no sentence is quoted: cardiomyopathy (1 paper); HIV-1 infection (1); renal carcinoma (1); tumor (1); type 2 diabetes mellitus (1).